AKT1 (AKT serine/threonine kinase 1)
Diseases named in the same sentence as AKT1 in open-access papers (continued):
Sharing a sentence is not in itself a finding about the gene and the disease.
osteosarcoma (159 papers, 2007 to 2026). A usually aggressive malignant bone-forming mesenchymal neoplasm, predominantly affecting adolescents and young adults. "In a dose- and time-dependent manner, MTF inhibited proliferation, migration and invasion of osteosarcoma cells and this effect was associated with decreased expression of phosphorylated AKT serine/threonine kinase 1 (p-Akt) and vimentin (VIM), and increased expression of PTEN and cadherin 1 (CDH1)." (PMID 30241339, 2018). "Emerging evidence indicates that MNAT1 promotes osteosarcoma pulmonary metastasis via AKT1 upregulation." (PMID 41235252, 2025). "Among the AKT isoforms, AKT1 is recognized as functionally dominant in osteoblast-like cells and osteosarcoma." (PMID 40862758, 2025). "Network pharmacology showed that 251 luteolin against osteosarcoma targets and 8 hub targets including AKT1, ALB, CASP3, IL6, JUN, STAT3, TNF, and VEGFA." (PMID 40066267, 2025). "Subsequently, HSP90 knockdown can lead to the reduced osteosarcoma cells viability and migration and the dramatically reduced protein levels of p-AKT1, AKT1, Vimentin, as well as ki-67." (PMID 37861934, 2023). "In osteosarcoma cells, AKT1 and senescence suppress the DDR function, such as homologous recombination for DNA repair, of the mediator of DNA damage checkpoint 1 (MDC1) by overexpressing miR-22-3p (miR-22)." (PMID 36835100, 2023). "In osteosarcoma, miR-19 targets RhoB and down-regulates its expression, inhibiting the dephosphorylation of Akt1 protein and promoting tumor cell metastasis." (PMID 35538494, 2022). "Without ALAPP treatment, the levels of CDK4 and AKT1 expression in MG-63 osteosarcoma cells were about 92.1% and 86% higher, respectively, than those of Cdk4 and Akt1 expression in MC3T3 osteoblasts." (PMID 37551169, 2022). "We present the evidence here that RhoA mediates Wnt5a-induced osteosarcoma cell migration via PI3Kα, Akt1 and Akt2 isoforms." (PMID 28289332, 2017). "Taken together, we demonstrate that RhoA acts as the downstream of PI3K/Akt signaling (specific PI3Kα, Akt1 and Akt2 isoforms) and mediated Wnt5a-induced the migration of osteosarcoma cells." (PMID 28289332, 2017). "Because Akt3 appears to be predominantly expressed in the brain, we used the specific inhibitors to block PI3Kα, PI3Kβ, PI3Kγ, PI3Kδ, Akt1 and Akt2 activity and studies the effects of each isoform of PI3Ks and Akts in osteosarcoma cell migration in this study." (PMID 28289332, 2017). "Furthermore, we also analyzed the correlation of SOX2 and AKT1 proteins in 12 human osteosarcoma protein profiling sequencing from the Orthopedic Oncology Database of Shanghai Changzheng Hospital." (PMID 39994220, 2025). "The cell experiment and specific assay for AKT1 inhibition showed they could inhibit the proliferation and AKT1 expression of MG63 cells (Osteosarcoma cells)." (PMID 35603567, 2022). "After treatment with 50 μg/mL ALAPP, the levels of expression of Cdk4 and Akt1 were unchanged in MC3T3 osteoblasts, but compared with levels in untreated cells, the levels of CDK4 and AKT1 expression were downregulated by about 42% and 43%, respectively, in MG-63 osteosarcoma cells." (PMID 37551169, 2022). "The AKT1 pathway was reported to be associated with chemoresistance in cancers, overexpression of phosphor-AKT1 and AKT1 was observed in cisplatin-resistant cancer cells, and downregulation of AKT was shown to reverse cisplatin resistance in osteosarcoma cells and non-small‐cell lung cancer cells." (PMID 36303126, 2022). "Here, PI3Kα, PI3Kβ, Akt1 and Akt2 isoforms regulate Wnt5a-induced osteosarcoma cell migration." (PMID 28289332, 2017). "This study shows that luteolin may regulate multiple signaling pathways by targeting various genes like AKT1, STAT3, IL6, TNF, and VEGFA to inhibit osteosarcoma proliferation and metastasis." (PMID 37749554, 2023). "ALAPP significantly downregulated the expression of HSP90, CDK4, and AKT1 expression in MG-63 osteosarcoma, but not in the osteoblasts." (PMID 37551169, 2022).
osteosarcoma (continued). "p-FLNC, AKT1, and MAPK signaling contributes to resistance to lobaplatin in osteosarcoma SaOS-2 cells and may represent molecular targets to overcome osteosarcoma chemoresistance." (PMID 34717622, 2021). "Experimental results showed that luteolin could inhibit cell viability and significantly decrease the expression of AKT1, STAT3, IL6, TNF, and VEGFA, and luteolin could also inhibit osteosarcoma proliferation and metastasis in osteosarcoma orthotopic mouse model." (PMID 37749554, 2023). "The immunohistochemical staining results showed that p-FLNC, AKT1 and p-ERK1/2 were highly expressed in platinum-resistant clinical specimens but weakly expressed in platinum-sensitive specimens, and platinum-resistant osteosarcoma specimens demonstrated weak expression of p-JNK." (PMID 34717622, 2021). "However, in MG-63 osteosarcoma cells, ALAPP failed to upregulate HSF1, and HSP90, CDK4, and AKT1 were downregulated to about the level seen in osteoblasts." (PMID 37551169, 2022).
atherosclerosis (158 papers, 2014 to 2026). A disease characterized by the build-up of fatty material and calcium deposition in the arterial wall resulting in partial or complete occlusion of the arterial lumen. "For instance, AKT1 deficiency in Akt1−/−Apoe−/− mice led to severe atherosclerosis that was attributed to reduced levels of NO and endothelial cell viability in atherosclerosis-susceptible areas." (PMID 38193847, 2024). "Researchers reported that, in apoE-deficient mice, the loss of Akt1 leaded to severe atherosclerosis and Akt3 deficiency in macrophages promoted foam cell formation and atherosclerosis." (PMID 35151267, 2022). "To dissect the impact of macrophage Akt1 and Akt2 on early atherosclerosis, we generated mice with hematopoietic deficiency of Akt1 or Akt2." (PMID 25240046, 2014). "Furthermore, loss of AKT1 attenuated the survival and migration of vascular smooth muscle cells and caused cardiac dysfunction in the setting of atherosclerosis." (PMID 40857258, 2025). "SMAD3, TNF, MMP2, MMP9, CTGF, CD44 and AKT1 are associated with atherosclerosis." (PMID 37328880, 2023). "Moreover, less cholesterol accumulation was observed in the macrophages of atherosclerosis-prone apolipoprotein E-deficient (ApoE‒/‒) mice who underwent Akt1‒/‒ bone marrow transplantation when exposed to modified lipoproteins." (PMID 31635197, 2019). "Interestingly, loss of Akt1 in Apoe−/− mice results in accelerated atherosclerosis, due to a protective role of Akt1 in endothelial cells." (PMID 25240046, 2014). "However, the impact of macrophage phenotypes generated by Akt1 and Akt2 deficiency on atherosclerosis remains unclear." (PMID 25240046, 2014). "By applying transcription analysis to study the Shexiang Baoxin pill (SBP) in atherosclerosis treatment, key target genes (MAPK3, AKT1, and STAT3) associated with the prescription’s efficacy were identified." (PMID 41282606, 2025). "In a previous study, network pharmacology was utilized to examine the therapeutic roles of canagliflozin and dapagliflozin in atherosclerosis, revealing that these drugs act by targeting key molecules such as Akt1, MAPK1, MAPK14, SRC, and EGFR." (PMID 40141782, 2025). "Migraine sufferers are more prone to developing arterial atherosclerosis, which contains eleven targets including Akt1, TNF, IL-6, etc.." (PMID 41009787, 2025). "AKT1 expression in vascular smooth muscle cells was also found to influence plaque vulnerability, thereby affecting atherosclerosis progression." (PMID 40857258, 2025). "Numerous studies reported FAK/AKT1 pathway participated in chronic inflammation and fibrosis, such as atherosclerosis, and lung and liver fibrosis." (PMID 38911067, 2024). "The lipid and atherosclerosis pathway, for example, involves several inflammation-related targets such as AKT1, TNF, and IL6, underscoring chronic inflammation’s critical role in atherosclerosis progression." (PMID 39822742, 2024). "These triple transgenic mice were developed to address the importance of the Akt1-eNOS activation cascade in an extreme model of murine atherosclerosis using genetic methods." (PMID 38034389, 2023). "AKT1 is a significant regulator of endothelial NO synthase activity and plays a role in atherosclerosis, inflammation, and angiogenesis." (PMID 36776258, 2023). "Multiple FOXO3a-regulated genes are involved in VSMC apoptosis, including apoptotic protease activating factor 1, which is known to be increased in human atherosclerosis, but reduced by AKT1 activity in vivo." (PMID 36675309, 2023).
atherosclerosis (continued). "The relationship between KEGG and Hub genes is as follows: 7 genes are enriched in the first pathway: Lipid and atherosclerosis, and AKT1 is enriched in 16 pathways, which explains that AKT1 has a regulatory effect on KEGG pathway." (PMID 37081038, 2023). "According to the PPI network, ALB and AKT1 are the primary targets for Xuefu Zhuyu Decoction therapy to cure atherosclerosis." (PMID 36532728, 2022). "AKT1 is the center of the PI3K-AKt signaling pathway, and inhibition of its overactivation can alleviate high-fatdiet-induced atherosclerosis in ApoE + mice." (PMID 36212940, 2022). "AKT1 is a major regulator of apoptosis in VSMCs that protects against arterial remodeling and atherosclerosis in vivo." (PMID 33321972, 2020). "This novel approach allowed us to compare the impact of expression of the individual Akt1 and Akt3 isoforms on macrophage viability and atherosclerosis." (PMID 31159424, 2019). "AKT1 expression in vascular smooth muscle cells influences early and late stages of atherosclerosis." (PMID 27251057, 2016). "That study showed that miR‐342‐5p promotes inflammatory macrophage activation through an Akt1 and miR‐155‐dependent pathway during atherosclerosis." (PMID 26176567, 2015). "Several studies reported the involvement of Akt1 in the development of atherosclerosis, macrophage inflammation, endothelial cell migration and vascular smooth muscle cell proliferation and protection against apoptosis." (PMID 25188469, 2014). "Active components such as beta-sitosterol, stigmasterol, and formononetin may regulate levels of phosphorylation such as Akt1 through the lipid and atherosclerosis and PI3K-Akt signaling pathways." (PMID 41009787, 2025). "AKT1, a key downstream kinase in this pathway, regulates apoptosis, cell proliferation, and inflammatory responses in smooth muscle cells, and plays a role in diseases such as atherosclerosis and pulmonary fibrosis." (PMID 41439108, 2025). "BBG-NEs may promote wound healing by affecting IL-17, AGE-AGEs, and lipid and atherosclerosis signaling pathways as well as pivotal targets like AKT1, CXCL8, and EGFR." (PMID 38731484, 2024). "Genes involved in fluid shear stress and atherosclerosis include IL1β, TNF, MMP9, AKT1, and NOX4; genes associated with AGE-RAGE signaling pathway in diabetic complications include AKT1, IL1β, and NOX4; while genes associated with HIF signaling pathway contain STAT3, NOX4, NFκB, and MAPK1." (PMID 36192741, 2022). "Genetically modified mice revealed the protective role of AKT1 in vascular function, with AKT1 KO mice on an ApoE−/− background displaying severe peripheral vascular disease, atherosclerosis, occlusive coronary artery disease, plaque vulnerability, and cardiac dysfunction." (PMID 35990823, 2022). "Our finding that GBH contains five core compounds (quercetin, kaempferol, baicalein, ellagic acid, and baicalin) that can be linked to six potential target genes (AKT1, CASP3, MAPK1, MAPK3, NOS2, and PTGS2) related to atherosclerosis is in agreement with previous reports." (PMID 33321972, 2020). "In endothelial cells and VSMCs, Akt1 could inhibit the formation of atherosclerosis and play a protective role." (PMID 33644113, 2020). "Macrophage Akt1 and Akt2 also have different effects on atherosclerosis." (PMID 25929188, 2015). "The detrimental effect of Akt1 deficiency on atherosclerosis was not reversible by reconstitution with wild-type bone marrow, demonstrating that the changes are mediated by vessel wall cells." (PMID 25929188, 2015). "Macrophages express three Akt isoforms, Akt1, Akt2, and Akt3, but the roles of Akt1 and Akt2 in atherosclerosis in vivo remain unclear." (PMID 25240046, 2014). "Thus, PI3Kg/Akt1 should be considered a fundamental molecular axis for the pathobiology of atherosclerosis." (PMID 25114952, 2014).
atherosclerosis (continued). "Finally, in vivo (rat/zebrafish) and in vitro (cell models) validations remain essential, exemplified by the Moluodan concentrated pill downregulating TNF-α/PI3K/p-Akt in gastritis and the Buyang huanwu decoction modulating the AKT1/MAPK1/PIK3CA axis against atherosclerosis." (PMID 40732361, 2025). "Therefore, WIPS1 and AKT1 may have a close relationship with human fatty acid intake on the formation of atherosclerosis, but the exact regulatory mechanism needs further study." (PMID 37537524, 2023). "However, the development of atherosclerosis was aggravated in Akt1 knockout mice." (PMID 34830282, 2021). "The opposing effects of Akt1 and Akt2 in macrophage M1/M2 polarisation, inflammation and cholesterol accumulation indicate that Akt isoforms might have completely different or even opposing effects on atherosclerosis." (PMID 25929188, 2015). "After extracted genes in lipid and atherosclerosis pathway, a new PPI was established, which was prompted that genes including AKT1, BCL-2, CAPS3 and PPARG would be the core genes worked." (PMID 41559682, 2026). "The shortest way in CTPDN mainly divided into three types, AKT1, lipid and atherosclerosis, CAT and chemical carcinogenesis—receptor activation, and AKT1 or HMOX1 with STAT1 together acting on fluid shear stress and atherosclerosis." (PMID 40217538, 2025). "The analysis also identified inflammation-related targets within lipid and atherosclerosis pathways, such as STAT3, MMP9, MMP1, and AKT1, emphasizing the role of chronic inflammation in atherosclerosis development." (PMID 39808649, 2025). "Network pharmacology and molecular docking analyses indicated that AKT1 and NOS3 (also known as eNOS) play crucial roles in GE alleviating atherosclerosis." (PMID 40718724, 2025). "Evidence from 2007 indicated that AKT1 deletion exacerbates atherosclerosis and occlusive CAD, as genetic ablation of AKT1 on an apolipoprotein E knockout background (ApoE(-/-)AKT1(-/-)) led to increased aortic lesion expansion and coronary atherosclerosis." (PMID 40857258, 2025). "The mRNA and protein expression of TGF-β, PPAR-γ, LXR-α, and ABCA1 in aortic and liver of atherosclerosis apoE−/− mice were upregulated (p < 0.05, p < 0.01), while those of PI3K and Akt1 were suppressed (p < 0.05, p < 0.01)." (PMID 41464973, 2025). "Consistent with our expectations, ex vivo experiments on atherosclerosis have demonstrated that NOB can interfere with the atherosclerotic process by modulating core targets, such as ALB, AKT1, and CASP3." (PMID 38468335, 2024). "Secondly, AKT1 and MMP9 are both enriched in multiple signaling pathways, such as Fluid shear stress and atherosclerosis, Lipid and atherosclerosis, AGE-RAGE signaling pathway in diabetic complications, and TNF signaling pathway." (PMID 38528143, 2024). "Mechanistically, the anti-inflammation and anti-atherosclerosis effects of NPRC deletion involved activation of cAMP/PKA pathway, leading to downstream upregulated AKT1 pathway and downregulated NF-κB pathway." (PMID 37553374, 2023). "We previously report worsened atherosclerosis in these eNOS+/+; Akt1−/−; ApoE−/− DKO mice, detailing the importance of Akt1 activity for vascular health." (PMID 38034389, 2023). "The results showed that the KEGG pathways in which AKT1 was involved included the TNF signaling pathway, MAPK signaling pathway, human cytomegalovirus infection, fluid shear stress and atherosclerosis, and hepatitis C." (PMID 34077310, 2021). "In cluster 1, AKT1 is effective in WNT signaling pathway, fluid shear stress and atherosclerosis and many studies confirm these roles." (PMID 29379595, 2017). "However, the roles of macrophage expression of Akt1 and Akt2 in atherosclerosis remain unclear." (PMID 25240046, 2014).
atherosclerosis (continued). "Cluster analysis emphasized IL6, TNF, AKT1, and VEGFA’s roles in atherosclerosis and inflammation." (PMID 38496269, 2024). "Indeed, genetic depletion of Akt1 induces endothelial cell dysfunction, reduces VSMC migration and survival, promotes atherosclerosis and coronary artery obstruction, and induces features of plaque vulnerability." (PMID 25929188, 2015). "The lack of impact of macrophage Akt1 on the extent of atherosclerosis is consistent with the observation that Akt1−/−Apoe−/− bone marrow was not sufficient to worsen atherogenesis in Apoe−/− recipient mice." (PMID 25240046, 2014). "The mechanism of action of kaempferol in treating OP may involve up-regulating the expression of AKT1 and down-regulating the expression of MMP9, while participating in the Atherosclerosis-related signaling pathways, AGE/RAGE signaling pathway, and TNF signaling pathway." (PMID 38528143, 2024). "Our results indicated that compounds in Tualang honey such as luteolin, fisetin, hesperitin, catechin, and kaempferol may have a crucial impact on atherosclerosis through their effects on key biological targets, including PIK3CA, SRC, P1K3R1, EGFR, PTPN11, and AKT1." (PMID 37174317, 2023). "The results of fluid shear stress and atherosclerosis enrichment pathway, AGE-RAGE signaling pathway, and PPI core protein ranking showed that VEGFA and AKT1 are closely related to the development of AS, and maybe the key regulatory proteins of XFZYD in the treatment of AS." (PMID 35960089, 2022). "Therefore, CSJD may regulate targets such as PIK3CA, AKT1, TNF, IL-6, and others through the lipid and atherosclerosis pathway, block the key pathways and molecules of lipid metabolism, and thus achieve the effect of inhibiting dengue virus replication and improving clinical symptoms of patients." (PMID 38206728, 2023). "Similarly, forced expression of Akt1 in VSMCs does not induce VSMC proliferation in normal arteries, after carotid ligation, or in atherosclerosis." (PMID 25929188, 2015).